CYP1B1 (cytochrome P450 family 1 subfamily B member 1)
Diseases named in the same sentence as CYP1B1 in open-access papers (continued):
Sharing a sentence is not in itself a finding about the gene and the disease.
cancer (continued). "These enzymes have cell-or tissue-specific expression, while some of them, particularly CYP1B1, are overexpressed in a wide range of cancers." (PMID 25516145, 2015). "From the cancer pathway-related genes analyzed, eight were down-regulated ~ 2- to 5- fold after CYP1B1 depletion and among them, CDC20 was the greatest." (PMID 26626260, 2015). "It is recognized that CYP1B1 is up-regulated and plays an essential role in carcinogenesis in several types of cancers." (PMID 26626260, 2015). "Heterologous expression of unmodified CYP1B1 in E. coli is difficult and, therefore, hampers research to evaluate important aspects of many cancers, pathomechanistic studies of PCG and understanding of various metabolic pathways." (PMID 25329831, 2014). "The data adds interesting insight into the contribution of CYP1 expression in cancer pathology and the potential use of CYP1 and mainly CYP1B1 enzymes in cancer therapy." (PMID 24358191, 2013). "Our data support the use of CYP1 and mainly CYP1B1 enzymes in cancer therapy, via the selective activation of non cytotoxic prodrugs to toxic metabolites." (PMID 24358191, 2013). "Perhaps heme directly regulates the expression of cytoglobin and cytochrome c, while a heme-independent mechanism contributes to the increased levels of CYP1B1 and Cox-2 in cancer cells." (PMID 23704904, 2013). "It was also demonstrated the implication of many allelic variations in CYP1B1 in modulating the incidence of several types of cancers." (PMID 24151610, 2013). "Results showed that CYP1B1 is upregulated in numerous cancers such as esophagus, lung, skin, breast, brain, testis, and colon cancers." (PMID 24151610, 2013). "The study reveals active CYP1 overexpression in human tumors and uncovers the potential use of CYP1 enzymes and mainly CYP1B1 as targets for cancer therapy." (PMID 24358191, 2013). "Both PBQs had potent inhibition against the activities of CYP1A1 and CYP1B1, the latter which is known to be a universal marker for cancer and a target for drug discovery." (PMID 22686946, 2012). "The CYP1 family of enzymes and in particular CYP1B1 appears to be a universal molecular cancer marker and a target for drug discovery." (PMID 22686946, 2012). "Allelic variations in CYP1B1 have also been shown to modulate the incidence of several types of cancers." (PMID 22114726, 2011). "Although we assayed B-cells, CYP1B1 is highly expressed in lung, likely in endothelial cells, and is recognized as a modifier gene for cancers." (PMID 18823550, 2008). "In conclusion, the results presented in this study provide more evidence about the potential of the cytochromes P450 CYP1A1 and CYP1B1 as targets in cancer therapy and prevention." (PMID 18454852, 2008). "Enhanced expression of this protein has been observed in a number of cancers and it has been demonstrated using CYP1B1-null mice that this enzyme enhances the carcinogenicity of the PAH 7,12-dimethylbenz(a)anthracene." (PMID 17042939, 2006). "CYP1B1 has been evaluated as a candidate gene for various cancers because of its function in activating environmental procarcinogens and catalysing the conversion of oestrogens to genotoxic catechol oestrogens." (PMID 14562027, 2003). "We report here that the cancer preventative agent resveratrol undergoes metabolism by the cytochrome P450 enzyme CYP1B1 to give a metabolite which has been identified as the known antileukaemic agent piceatannol." (PMID 11875742, 2002). "On the other hand, CYP1B1 overexpression in cancer cells may be disadvantageous if this enzyme can metabolize the therapeutics to inactive forms." (PMID 39940769, 2025). "CYP1B1 may mediate chemoresistance by deactivating the polyene paclitaxel, thereby promoting cancer cell survival, stemness, and resistance to paclitaxel in lung cancer." (PMID 40435846, 2025).
cancer (continued). "Using Gene Set Enrichment Analysis, we identified the top five signalling pathways enriched in CYP1B1: chemokine signalling pathway, FA, neuroactive ligand-receptor interaction, cancer-related pathways, and actincytoskeleton regulation (Panel B in the Online Supplementary Document)." (PMID 41267622, 2025). "The expression of CYP1B1 can be epigenetically regulated in cancer cells." (PMID 41155673, 2025). "Inhibiting CYP1B1 could prevent the formation of harmful intermediates, slow down cancer progression, sensitize tumors to chemotherapy, and improve clinical outcomes." (PMID 40883330, 2025). "Since CYP1B1 gene expression is influenced by exogenous activation of the AhR pathway by PAHs and related environmental pollutants, its expression in cancer patients may vary depending on lifestyle and environmental exposures." (PMID 41009721, 2025). "Both ABCB1 and CYP1B1 correlated with microRNAs in cancer and the Nuclear Receptors Meta-Pathway." (PMID 38534761, 2024). "In this study, we have analyzed the expression of AhR in a series of diffuse and intestinal gastric tumors, as well as the expression of xenobiotic metabolic enzymes such as cytochromes P450 (CYP1A1 and CYP1B1) and a large panel of genes known to be regulated by AhR in several cancers." (PMID 39200369, 2024). "CYP1B1 activates a large number of pollutants which may result in the activation of pro-cancer signaling pathways." (PMID 39200369, 2024). "Polymorphisms in the CYP1B1 gene have also been studied to show that combinations of some of them are associated with an increased PCa risk, whereas one frequent haplotype (TATGT) is associated with a decreased cancer risk." (PMID 39682707, 2024). "Moreover, in many kinds of cancer, the increase in CYP1B1 expression can be due to the tumor itself, and we cannot be sure that in RCC its expression is due to cisplatin treatment." (PMID 37371125, 2023). "Ferroptosis plays an important role in cancer immunotherapy, thus we aimed to determine whether CYP1B1 disrupts the effectiveness of anti-PD-1 therapy." (PMID 37059712, 2023). "Recently, CYP1B1 was also shown to enhance the resistance of cancer cells to ferroptosis and immunotherapy, particularly anti-PD-1, through the activation of the protein kinase C (PKC) cascade and the degradation of acyl-CoA synthetase long-chain family member 4 (ACSL4)." (PMID 38001897, 2023). "Although it is possible that CYP1B1 may play different roles in regulating drug resistance in different cancer types, the inhibition of CYP1B1 activity has been considered to be a therapeutic target for improving chemotherapy." (PMID 37229486, 2023). "Additionally, CYP1B1 depletion was shown to reduce the growth, invasion, and migration of cancer cells through the upregulation of cell division cycle 20 homolog (CDC20) and down-regulation of death-associated protein kinase-1 (DAPK1)." (PMID 38001897, 2023). "Moreover, the inhibition of CYP1B1 expression in cancer cells enhanced treatment efficacy and overcame cancer cells’ resistance to anti-PD-1 therapy." (PMID 38001897, 2023). "Interestingly, we found that carcinoma patients with higher renal CD133/CYP1B1 expression had better outcomes compared to those with lower CD133/CYP1B1 expression (p = 0.05 and p = 6 × 10−4, respectively)." (PMID 37371125, 2023). "Combined with previous studies, the morphological (from the histological and TEM experiments) findings on kidney injury of the present study suggest that CYP1B1 plays a key role in cancer angiogenesis, acting both in cancer cells and the tumor microenvironment." (PMID 35678542, 2022). "Furthermore, the highly upregulated expression of CP4Z1, CYP1B1, and CYP2A7 in cancer cells was associated with their increased resistance to a variety of chemotherapeutic agents." (PMID 35206262, 2022). "Elevated levels of CYP1B1 are reported in many types of cancer." (PMID 36077068, 2022).
cancer (continued). "Although melatonin has been identified to exhibit tumor suppressing activity, the role and mechanism of the clinical and immunological characteristics of CYP1B1 in cancer remain unclear." (PMID 36428734, 2022). "Finally, the immunological CYP1B1 in pan-cancer needs additional investigation to clarify its function and processes." (PMID 36428734, 2022). "CYP1B1 was significantly downregulated in most of the cancers." (PMID 36428734, 2022). "The results indicated that the dysregulated expression of CYP1B1 was correlated with clinical and immunological characteristics in cancer and could be a promising predictor and molecular target for clinical immune treatment." (PMID 36428734, 2022). "Based on importance and function of mRNA more than conventional translation, CYP1B1 may also serve as a universal cancer marker." (PMID 36418939, 2022). "Recently, CYP1B1 has emerged as a key player in chemotherapy resistance in the treatment of cancer." (PMID 35752630, 2022). "The results indicated that CYP1B1 was correlated with clinical characteristics in cancer and could be a prognostic predictor in cancer." (PMID 36428734, 2022). "Studies indicate a relationship between CYP1B1 and aggressive cancer phenotypes." (PMID 36077068, 2022). "This loop is autoregulated by AHR-dependent elevation of the AHR repressor, and CYP1A1 and CYP1B1 enzymes that metabolize kynurenine ligands to decrease their bioavailability, thus forming a cancer progression circuit where AHR-regulated CYP1B1 levels correlate with AHR activity." (PMID 36077068, 2022). "Therefore, the development of CYP1B1-based therapeutic strategies would be a great advantage for the treatment of cancers expressing CYP1B1." (PMID 34636736, 2021). "Additionally, CYP1B1 overexpression reduced the sensitivity of cancer cells to anti-cancer drugs such as paclitaxel and docetaxel and induced drug resistance." (PMID 33692504, 2021). "Therefore, CYP1B1 is a tumor biomarker, and the inhibition of CYP1B1 activity is considered to be a therapeutic target for cancer chemoprevention and chemotherapy." (PMID 34680513, 2021). "Paradoxically, the CYP1B1 enzymes have been reported to be involved in the activation of procarcinogens, and high expression of these enzymes have been observed in different human cancers." (PMID 34164422, 2021). "Family 1 Subfamily A Member 1 (CYP1A1) and Family 1 Subfamily B Member 1 (CYP1B1) might play a role in cancer pathogenesis and prognosis." (PMID 33906313, 2021). "Several studies have indicated selective CYP1B1 expression in many cancers." (PMID 34636736, 2021). "Taken together, the current knowledge and understanding of cancer-selective CYP1B1 expression may hopefully lead to the discovery of novel CYP1B1-based therapeutic strategies." (PMID 34636736, 2021). "Importantly, CYP1B1 is also a target for immunotherapy for late stages of cancer, where CYP1B1 vaccination increases the patients’ overall outcome." (PMID 34636736, 2021). "Taken together, these results propose that the CYP1B1 enzyme might be a driver in tumour malignancy and it, therefore, represents a tumour biomarker and a potential target for the development of new cancer therapeutic strategies." (PMID 33692504, 2021). "In this work, no statically significant association was identified between CYP1B1 genotypes with neither odd of cancer risk nor with its stage or grade, except for the CC genotype, which is associated with poor differentiation." (PMID 33906313, 2021). "For instance, in endothelial cells, CYP1B1 was observed to promote endothelial nitric oxide synthase (eNOS) expression as well as nitric oxide levels, responsible for the many inflammatory and angiogenesis effects important for cancer progression." (PMID 33185690, 2020). "Therefore, the regulation of CYP1B1 expression can act as a therapeutic strategy, especially for cancer treatment." (PMID 32726968, 2020).
cancer (continued). "In addition, we found significant downregulation of multiple cancer-related genes coding for cytochrome P450 1B1 (CYP1B1), C-C chemokine receptor type 2 (CCR2), stabilin-1 (STAB1) and transmembrane protein 176B (TMEM176B)." (PMID 32780768, 2020). "Moreover, a CYP1B1 vaccine known as Zyc300 is presently in phase I and II trials that aim to destroy cancer cells through T-cell response induction." (PMID 31998435, 2020). "CYP1B1 inhibitors can be utilized to understand the CYP1B1 function; thus, it might be considered as anti-cancer agents for the treatment of certain types of cancer." (PMID 32626511, 2020). "Interestingly, dietary flavonoids can be metabolized by CYP1B1 to products that can inhibit cancer proliferation." (PMID 32626511, 2020). "Second, we will briefly discuss the role of CYP1B1 in both cardiovascular diseases and cancer." (PMID 33185690, 2020). "This study shows the ability of CYP1B1 to interfere with cancer treatments." (PMID 33185690, 2020). "As discussed in this review, there is growing evidence that CYP1B1 is an attractive target wherein its inhibition may offer protection against cancer treatment-induced cardiovascular toxicity and prevent chemo/radio-resistance at the same time." (PMID 33185690, 2020). "Long-term F. nucleatum stimulation may increase the risk of cell carcinogenesis by altering many inflammation- and cancer-related genes and pathways, such as Mnda, Cyp1b1, Comp, Phex, Mmp3, Tnfrsf1b, Fbln5, and Nfkb2." (PMID 33042984, 2020). "Interestingly, CYP1B1 is a direct target gene for miR-187-5p, which is expressed during cancer cell growth." (PMID 32626511, 2020). "In addition, highly upregulated expression of CP4Z1, CYP1B1, and CYP2A7 in cancer cells was associated with their enhanced resistance to a variety of chemotherapeutics." (PMID 32370233, 2020). "Since CYP1B1 is involved in the metabolism of catechol estrogen and the formation of a toxicologically active metabolite, 4-hydroxyestradiol, the inhibition of CYP1B1 is an attractive target for hormonally driven cancers such as breast." (PMID 32331450, 2020). "Interestingly, some anti-cancer drugs used in clinics are competitive inhibitors of CYP1B1, such as flutamide, paclitaxel, mitoxantrone, and docetaxel." (PMID 32626511, 2020). "A growing body of evidence is demonstrating a detrimental role of CYP1B1 in both cardiovascular diseases and cancer, via perturbed metabolism of endogenous compounds, production of carcinogenic metabolites, DNA adduct formation, and generation of reactive oxygen species (ROS)." (PMID 33185690, 2020). "This contradicts the observation that CYP1B1 was overexpressed in many cancers." (PMID 31331382, 2019). "Recently, CYP1B1's role in cancer progression and metastasis was reported." (PMID 30147715, 2018). "Previous studies ascertained that estrogens up-regulate CYP1B1 levels through ERα in diverse cancer cells, therefore we asked whether estrogens may trigger CYP1B1 expression through GPER in an ER-independent manner." (PMID 29290975, 2017). "Taken together, these findings suggest that CYP1B1 might be a driver in cancer progression and, therefore, represent a significant cancer biomarker and potential target for anticancer therapy." (PMID 26981862, 2016). "CYP1B1 expression is induced in vascular endothelial cells, thymus/marrow and immune cells, breast, prostate, uterus, epithelial lining of the head and neck and upper GI tract, and various types of cancers." (PMID 27894333, 2016). "The overexpression of CYP1B1 proteins in cancer cells may affect their sensitivity in reacting to anticancer drugs." (PMID 25516145, 2015). "In addition, CYP1B1 up-regulation is also thought to contribute to the chemoresistant phenotype of cancers." (PMID 25860934, 2015).
cancer (continued). "In cancer cells, CYP1B1 might induce changes in the response to drugs due to CYP1B1 activation of prodrugs, such as resveratrol, and inactivation of other drugs, such as tamoxifen and docetaxel." (PMID 24699256, 2014). "However, CYP1B1 is expressed in endothelial cells and its expression promotes angiogenesis in a non-cancer mouse model." (PMID 24023955, 2013). "To further prove that CYP1B1 is notably responsible for the activity determined in tumors, we performed incubation of microsomes isolated from cancer tissue with the substrate diosmetin, in the presence of a polyclonal CYP1B1 antibody (Santa Cruz, Heidelberg, Germany) at 1:500 dilution." (PMID 24358191, 2013). "As a result CYP1B1 is considered a potential tumor marker and a putative target for cancer therapy." (PMID 24358191, 2013). "CYP1B1 over-expression in cancer has been previously reported." (PMID 24023955, 2013). "Consequently CYP1B1 expression in patients with cancer varies amongst other factors, according to lifestyle and social habits." (PMID 24358191, 2013). "In addition, it showed potent inhibition against CYP1B1 enzyme activities, a marker for cancer and target for drug discovery." (PMID 22686946, 2012). "CYP1B1 is thought to contribute to the anti-proliferative effects of several dietary compounds by metabolizing them into products exhibiting additional cytotoxicity within cancer cells." (PMID 21510869, 2011). "Interestingly, enhanced expression of this enzyme has been observed in a number of cancers and it has been demonstrated, in experiments involving CYP1B1-null mice, that it enhances the carcinogenicity of 7,12-dimethylbenz[a]anthracene." (PMID 21714911, 2011). "CYP1B1 is a cytochrome P450 enzyme overexpressed in a variety of malignant tumours." (PMID 15280921, 2004). "We then realised the similarity in molecular structure of the anticancer prodrugs we had designed specifically for CYP1B1 to the molecular structure of certain natural products that have cancer preventative properties, and in particular the phytoestrogens such as resveratrol." (PMID 11875742, 2002). "The presence of CYP1B1 may be of importance in the modulation of these tumours to anti-cancer drugs." (PMID 11461084, 2001). "Interestingly, most of the effects of knocking down ADAM12 and CYP1B1 were observed in overweight and obese‐derived adipocytes, confirming the relevance of these two genes not only in tumorigenesis but also in the crosstalk between adipose tissue and cancer." (PMID 39806854, 2025). "Thus, the potent molecular interaction of docetaxel with ABCB1 and CYP1B1 may insinuate potential resistance of the cancer cells to docetaxel via increased expression of ABCB1 and CYP1B1." (PMID 38534761, 2024). "The differential CYP1A1 and CYP1B1 expressions in normal tissues and tumour tissues may provide an opportunity for the development of tumour-selective drugs for the effective treatment of a variety of different cancers." (PMID 38257336, 2024). "Cytochromes CYP1A1, CYP1A2, and CYP1B1, the members of the cytochrome P450 family 1, catalyze the metabolism of endogenous compounds, drugs, and non-drug xenobiotics which include substances involved in the process of carcinogenesis, cancer chemoprevention, and therapy." (PMID 37511239, 2023). "Of the CYP450 enzymes, CYP1B1, 2C8, 3A4, and 3A5 have been reported to be correlated to cancer resistance, with CYP1B1 being mostly studied, which is found to be exclusively overexpressed in various types of cancers but has relatively low expression in normal tissues." (PMID 37229486, 2023). "Interestingly, CYP1B1 is overexpressed in multiple malignant tumors." (PMID 37059712, 2023). "Given the lack of connection between the mechanisms of action of these essential drugs, which form the foundation of the vast majority of chemotherapy regimens, CYP1B1-mediated resistance may be negatively impacting treatment outcomes for most cancer patients who receive chemotherapy." (PMID 35752630, 2022).